TMEM131L (transmembrane 131 like)
Description:
[Isoform 1]: Membrane-associated form that antagonizes canonical Wnt signaling by triggering lysosome-dependent degradation of Wnt-activated LRP6. Regulates thymocyte proliferation.
Synonyms: KIAA0922; DKFZp586H1322
Tractability: Antibody: UniProt places it where antibodies can reach, with high confidence; its Gene Ontology location is reachable by antibodies, with high confidence; UniProt predicts a signal peptide or a membrane-spanning region. PROTAC: ubiquitination databases record sites on it.
Gene: Protein-coding gene on chromosome 4 (153,466,307 to 153,637,612, forward strand). Ensembl gene ENSG00000121210.
Subcellular location: Cell membrane; Cytoplasm; Endoplasmic reticulum (Isoform 1); Cytoplasm (Isoform 5)
Subcellular location (Human Protein Atlas): Vesicles; Nucleoli fibrillar center
Gene Ontology:
Biological process: negative regulation of canonical Wnt signaling pathway; negative regulation of immature T cell proliferation in thymus
Cellular component: cytoplasm; endoplasmic reticulum; plasma membrane
Genetic constraint (gnomAD): Loss-of-function variants: 34 observed, 111.97 expected, observed/expected ratio (o/e) 0.3, 90% interval 0.23 to 0.4. The upper end of that interval is the gene's LOEUF score, 0.4, which puts it in group 1 of 6, group 1 being the genes least tolerant of losing a copy. Missense variants: 1,349 observed, 1,463.6 expected, observed/expected ratio (o/e) 0.92, 90% interval 0.88 to 0.96. Synonymous variants: 512 observed, 536.24 expected, observed/expected ratio (o/e) 0.95, 90% interval 0.89 to 1.03.
Homologues: Orthologues: chimpanzee TMEM131L (99% identical), macaque TMEM131L (95% identical), dog TMEM131L (88% identical), guinea pig TMEM131L (81% identical), pig TMEM131L (81% identical), rat Tmem131l (77% identical), mouse Tmem131l (77% identical), rabbit TMEM131L (76% identical), tropical clawed frog tmem131l (48% identical), zebrafish tmem131l (33% identical), Caenorhabditis elegans tmem-131 (15% identical), Drosophila melanogaster Tmem131 (14% identical). Paralogues in human: TMEM131 (24% identical).
Diseases named in the same sentence as TMEM131L in open-access papers:
TMEM131L is named in the same sentence as 12 diseases in open-access papers, as found by Europe PMC text mining. Sharing a sentence is not in itself a finding about the gene and the disease. The quoted sentences say what the papers report.
brain tumor (1 paper, 2023). "It was found that TMEM131L may be highly expressed in brain tumor tissues." (PMID 37090987, 2023).
glioblastoma (1 paper, 2023). The most malignant astrocytic tumor (WHO grade IV). "Meanwhile, the high expression of TMEM131L in histological subtypes of glioblastoma and oligodendroglioma was significant." (PMID 37090987, 2023).
cancer (2 papers, 2018 to 2023). A tumor composed of atypical neoplastic, often pleomorphic cells that invade other tissues. "This study was carried out to understand the role of TMEM131L mutations in pan-cancer, especially in GBM and LGG." (PMID 37090987, 2023). "The relationship between TMEM131L and several important genes was examined to determine whether the expression of TMEM131L in pan-carcinomas impacts the molecular mechanisms of cancer." (PMID 37090987, 2023). "The pan-carcinoma expression differential map subsequently revealed that elevated expression of TMEM131L may be a sign of GBM." (PMID 37090987, 2023). "The differential expression of TMEM131L in pan-carcinoma was analyzed." (PMID 37090987, 2023). "In this study, it has been shown that scatter plots of TMEM131L significantly correlated with TOP3 in stroma, immune, and ESTIMATE scores in pan-carcinoma." (PMID 37090987, 2023).
tumor (1 paper, 2023). "Moreover, a significantly high expression of TMEM131L was observed in tumor tissues of the GBMLGG cohort." (PMID 37090987, 2023). "Analysis of differential expression of TMEM131L between nontumor tissues and unpaired and paired samples of tumor tissues in TCGA and the GTEx pancarcinoma database indicated that differential expression of TMEM131L was significant in most tumors, including glioma." (PMID 37090987, 2023).
TMEM131L also shares sentences with these, for which no sentence is quoted: breast carcinoma (2 papers); Alzheimer disease (1); Esophageal Carcinoma (1); inflammatory bowel disease (1); oligodendroglioma (1); schizophrenia (1); systemic lupus erythematosus (1); type 1 diabetes (1).